MTMR3 (myotubularin related protein 3)
Description:
Lipid phosphatase that specifically dephosphorylates the D-3 position of phosphatidylinositol 3-phosphate and phosphatidylinositol 3,5-bisphosphate, generating phosphatidylinositol and phosphatidylinositol 5-phosphate. Decreases the levels of phosphatidylinositol 3-phosphate, a phospholipid found in cell membranes where it acts as key regulator of both cell signaling and intracellular membrane traffic. Could also have a molecular sequestering/adapter activity and regulate biological processes independently of its phosphatase activity. It includes the regulation of midbody abscission during mitotic cytokinesis.
Synonyms: FYVE-DSP1; KIAA0371; ZFYVE10
Tractability: Antibody: UniProt places it where antibodies can reach, with high confidence. PROTAC: ubiquitination databases record sites on it; its protein half-life has been measured.
Gene: Protein-coding gene on chromosome 22 (29,883,141 to 30,030,868, forward strand). Ensembl gene ENSG00000100330.
Subcellular location: Cytoplasm, cytosol; Membrane
Subcellular location (Human Protein Atlas): Nucleoplasm; Cytosol
Pathways (Reactome):
Autophagy: Macroautophagy
Metabolism: Synthesis of PIPs at the plasma membrane
Gene Ontology:
Molecular function: molecular adaptor activity; phosphatidylinositol-3,5-bisphosphate 3-phosphatase activity; phosphatidylinositol-3-phosphate phosphatase activity; protein binding; protein phosphatase binding; protein serine/threonine phosphatase activity; protein tyrosine phosphatase activity; protein tyrosine/serine/threonine phosphatase activity; metal ion binding
Biological process: cellular response to glucose starvation; midbody abscission; phosphatidylinositol 5-phosphate metabolic process; phosphatidylinositol dephosphorylation; protein dephosphorylation; regulation of autophagosome assembly; regulation of phosphatidylinositol dephosphorylation; macroautophagy; phosphatidylinositol biosynthetic process
Cellular component: cytoplasm; cytosol; membrane
Genetic constraint (gnomAD): Loss-of-function variants: 26 observed, 119.44 expected, observed/expected ratio (o/e) 0.22, 90% interval 0.16 to 0.3. The upper end of that interval is the gene's LOEUF score, 0.3, which puts it in group 1 of 6, group 1 being the genes least tolerant of losing a copy. Missense variants: 1,181 observed, 1,510.6 expected, observed/expected ratio (o/e) 0.78, 90% interval 0.74 to 0.82. Synonymous variants: 543 observed, 567.94 expected, observed/expected ratio (o/e) 0.96, 90% interval 0.89 to 1.03.
Homologues: Orthologues: macaque MTMR3 (98% identical), chimpanzee MTMR3 (97% identical), dog MTMR3 (92% identical), pig MTMR3 (89% identical), rabbit MTMR3 (89% identical), guinea pig MTMR3 (88% identical), mouse Mtmr3 (87% identical), rat Mtmr3 (87% identical), tropical clawed frog mtmr3 (65% identical), Drosophila melanogaster CG3632 (35% identical), zebrafish mtmr3 (25% identical), Caenorhabditis elegans mtm-3 (21% identical), and 11 more. Paralogues in human: MTMR4 (47% identical), MTMR2 (19% identical), SBF1 (18% identical), MTM1 (18% identical), SBF2 (18% identical), MTMR1 (18% identical), MTMR6 (17% identical), MTMR7 (17% identical), MTMR8 (17% identical), MTMR9 (14% identical), MTMR10 (12% identical), MTMR12 (11% identical), and 1 more.
Diseases named in the same sentence as MTMR3 in open-access papers:
MTMR3 is named in the same sentence as 39 diseases in open-access papers, as found by Europe PMC text mining. Sharing a sentence is not in itself a finding about the gene and the disease. The quoted sentences say what the papers report.
gastric cancer (11 papers, 2018 to 2024). A primary or metastatic malignant neoplasm involving the stomach. "Similar findings were found to MTMR3 T allele genotype rs12537, which showed a high risk and poor prognosis of gastric cancer." (PMID 37910386, 2023). "MiR-181a was found to be a modulator of autophagy in gastric cancer cells by downregulation of Myotubularin-related protein 3 (MTMR3)." (PMID 37456780, 2023). "Ectopic expression of miR-181a mimics or introduction of MTMR3 small interfering RNA resulted in an increase in cell proliferation, colony formation, migration, invasion, as well as suppression of apoptosis in gastric cancer." (PMID 34395483, 2021). "rs12537 CT genotype carriers in gastric cancer had low MTMR3 mRNA expression than CC genotype carriers." (PMID 34395483, 2021). "rs12537 associated gene, MTMR3, was reported to be associated with RA and SLE, gastric cancer and breast cancer." (PMID 34395483, 2021). "The overexpression of circMCTP2 in gastric cancer can restore MTMR3 expression in gastric cancer cells to cisplatin through sponging miR-99a-5p, which also affects the process of macrophage reprogramming TAMs." (PMID 34926295, 2021). "The SNP rs12537 present in the miR-181a-binding site in the 3' UTR of the MTMR3 gene and T/C variant in MTMR3 were reported to be associated with IgA nephropathy, RA, SLE and gastric cancer." (PMID 34395483, 2021). "miR-181a was found to be significantly up-regulated, while MTMR3 was found to be down-regulated in human gastric cancer (GC) tissues and cell lines." (PMID 30266744, 2018). "CircMCTP2 could repress gastric cancer cisplatin resistance via regulating the miR-99a-5p/MTMR3 signaling, revealing that circMCTP2 might be important for malignant tumor progression." (PMID 35475453, 2022). "In gastric cancer, the circular RNA MCTP2 impedes cisplatin resistance by inducing Myotubularin Related protein 3 (MTMR3) expression via miR-99a-5p." (PMID 39293372, 2024). "Indeed, only overexpression of miR-181a significantly reduced MTMR3, whereas knockdown of endogenous miR-181a did not elevate MTMR3 mRNA and protein levels in gastric cancer cell lines, arguing that MTMR3 may be deregulated by other factors in addition to miR-181a16,17." (PMID 31444373, 2019).
breast carcinoma (10 papers, 2015 to 2025). "The MTMR3 protein has been confirmed to be associated with the proliferation, migration, and autophagy of tumor cells in breast cancer." (PMID 40165954, 2025). "The MTMR3 rs12537 “T/T” genotype was highly expressed in cases of breast cancer (early and metastatic) compared to controls (risk genotype)." (PMID 37910386, 2023). "Our results show a statistically low but significant association between MTMR3 alleles and breast cancer." (PMID 37910386, 2023). "The “T” allele is a risk allele for breast cancer; participants with the “T” allele of the MTMR3 gene are twice as likely as those with the “C” allele to develop breast cancer." (PMID 37910386, 2023). "We also investigated the association of their SNPs (HULC rs7763881 and MTMR3 rs12537) with the susceptibility to breast cancer (BC) and fibroadenoma." (PMID 37910386, 2023). "The MTMR3 genotypes and breast cancer had a statistically significant but moderate association." (PMID 37910386, 2023). "Furthermore, we found rs12537 associated gene MTMR3 was lower expressed in breast cancer tissues but highly methylated." (PMID 34395483, 2021). "Moreover, rs12537 associated gene MTMR3 is lowly expressed but highly methylated in breast cancer." (PMID 34395483, 2021). "Our findings reveal that MTMR3 and HULC serum expression and their SNPs (HULC rs7763881, MTMR3 rs12537) are associated with a higher risk for the development of breast cancer in the Egyptian population." (PMID 37910386, 2023). "Similar to this, MTMR3 expression was considerably higher in breast cancer tissues compared to normal tissues." (PMID 37910386, 2023). "Kaplan–Meier OS analysis of breast cancer patients revealed that low expression of FBXW7, SRGAP2, MTMR3 as well as CDC42, the partner of CDC42BPA, is associated with poor prognosis." (PMID 37463901, 2023). "Participants with ‘T/T’ genotype of the MTMR3 gene have 3.9-times higher odds of developing breast cancer than those with ‘C/C’ genotype." (PMID 37910386, 2023). "Breast cancer patients exhibited elevated serum MTMR3 and HULC compared to fibroadenomas and control cases." (PMID 37910386, 2023). "Based on TCGA database, we found that MTMR3 gene was lower expressed in breast cancer tissues than normal tissues and the promoter methylation level was higher." (PMID 34395483, 2021). "More specifically, miR-100 has been shown to regulate apoptosis and cell cycle arrest through regulating myotubularin related protein 3 (MTMR3) in breast cancer cells." (PMID 28642484, 2017). "The data were consistent with the expression profiles in breast cancer cells, suggesting that MTMR3 was a target gene of miR-100 in SK-BR-3 cells." (PMID 26130569, 2015). "We detected the expression level of MTMR3 in the breast cancer cells and found significantly decreased levels in SK-BR-3 cells compared with other breast cancer cells." (PMID 26130569, 2015). "The interaction between miR-100 and MTMR3 mRNA was further evaluated in breast cancer cells in vivo." (PMID 26130569, 2015). "This indicated that MTMR3 had functions in cell cycle arrest and apoptosis induction in breast cancer cells." (PMID 26130569, 2015). "Research indicates that the high expression level of MTMR3 may be correlated with a lower overall survival period and a shorter recurrence-free survival period in breast cancer patients." (PMID 40165954, 2025). "Instead, MTMR3 expression was lower in breast cancer tissues than in normal tissues, but it was heavily methylated, suggesting that the rs12537 mutation in patients with estrogen receptor-positive breast cancer may control MTMR3 methylation." (PMID 37910386, 2023). "High MTMR3 expression levels may be detrimental to patients with breast cancer in terms of overall survival and relapse-free survival." (PMID 37910386, 2023). "MTMR3 was reported to contribute to immunological diseases such as RA and SLE, as well as gastric and breast cancer." (PMID 37910386, 2023).
oral cancer (7 papers, 2014 to 2025). "Another study led to the conclusion that miR-99a repressed oral cancer cell migration and invasion partly through decreasing myotubularin related protein 3 (MTMR3) expression." (PMID 33806361, 2021). "And a new role of MTMR3 was revealed in oral cancer last year as a downstream regulator of MiR-99a in the antimetastasis process." (PMID 25215329, 2014). "Moreover, a previous report highlighted that miR-99a-5p targets the same site of MTMR3 to regulate human oral cancer cell migration and invasion." (PMID 32235323, 2020). "For example, the lack of MTMR3 was shown to repress the proliferative and invasive potential of oral cancer cells." (PMID 32560331, 2020).
glioma (6 papers, 2021 to 2025). A benign or malignant brain and spinal cord tumor that arises from glial cells (astrocytes, oligodendrocytes, ependymal cells). "In glioma, miR-10a-5p promotes tumorigenesis by targeting myotubularin-related protein 3 (MTMR3) and modulating the Wnt/β-catenin signaling pathway, leading to increased cell proliferation and invasion." (PMID 39796267, 2025). "And miR-10a can promote glioma invasion and migration by targeting the 3′ untranslated region of myotubularin-related protein 3 (MTMR3), which regulates the wnt/β-catenin signaling pathway." (PMID 36479040, 2022). "MTMR3 modulates the proliferative phenotype and apoptosis of glioma cells by mediating the Wnt/β-catenin pathway and correlates with glioma grade." (PMID 34781885, 2021). "Silencing of fat mass and obesity-associated protein (FTO) enhanced m6A-dependent pri-miR-10a processing, facilitating miR-10 maturation and subsequent suppression of myotubularin-related protein 3 (MTMR3) expression, which ultimately contributed to glioma progression." (PMID 41039196, 2025).
lung carcinoma (5 papers, 2012 to 2017). "So far, GWAS have identified some important lung cancer susceptibility loci: 22q12 (MTMR3-HORMAD2), 3q28 (TP63) and 5p15 (TERT-CLPM1L)." (PMID 28903315, 2017). "The 22q12 locus harbouring MTMR3 has now also been associated with lung cancer, with specific MTMR3 mutations discovered in gastric and colorectal cancer, all of which may be important in the context of the emerging role of autophagy in cancer biology." (PMID 24710487, 2012). "It has been reported that the exogenous expression of MTMR3 could suppress the growth of lung cancer cells." (PMID 26130569, 2015). "In lung cancer cells, the increased expression of the MTMR3 gene activates p2721." (PMID 26130569, 2015).
Crohn disease (3 papers, 2015 to 2025). A gastrointestinal disorder characterized by chronic inflammation involving all layers of the intestinal wall, noncaseating granulomas affecting the intestinal wall and regional lymph nodes, and transmural fibrosis. "The variant in MTMR3 associated with increased Crohn disease risk results in increased MTMR3 expression, and in turn, reduced levels of autophagy in human macrophages." (PMID 40910070, 2025). "An SNP (rs713875) in MTMR3 was found to be significantly associated with Crohn's disease susceptibility by GWAS." (PMID 39883213, 2024). "One important study showed that the rs713875 Crohn's disease risk polymorphism enhanced MTMR3 expression, which in turn increased NOD2-induced caspase-1 activation, NF-κB signaling, and cytokine secretion, and lowered PI3P thus inhibiting autophagy." (PMID 39883213, 2024). "At rs713875 (MTMR3 locus), 30 reads containing the Crohn’s disease risk C allele and 9 reads containing the G allele were aligned using any level of genotype information (binomial P = 1.1x10−3)." (PMID 26210163, 2015).
IgA nephropathy (3 papers, 2019 to 2022). "Variants of MTMR3 have also recently been implicated in lupus nephritis and IgA nephropathy, implicating MTMR3 as important for renal function and immune regulation." (PMID 35990004, 2022). "The MTMR3 rs9983 high-risk allele at 22q12 showed associations with lupus nephritis, with lower MTMR3 transcription levels were recorded in blood samples with the rs9983 high-risk allele and in renal biopsies from lupus nephritis and IgA nephropathy patients." (PMID 31444373, 2019).
lupus nephritis (3 papers, 2015 to 2022). Glomerulonephritis in the context of systemic lupus erythematosus. "Expression analysis revealed lower MTMR3 transcriptions in the blood samples with this variant and in renal biopsy samples from lupus nephritis patients." (PMID 26506346, 2015). "Zhou and colleagues identified a significant association between a genetic variant of MTMR3 (rs9983A) and the risk of lupus nephritis in northern Han Chinese populations." (PMID 26506346, 2015). "Indeed, genetic variation in the MTMR3 gene was associated with autoimmune IgA nephropathy in lupus nephritis, which is a major disease manifestation in SLE patients." (PMID 31444373, 2019).
systemic lupus erythematosus (3 papers, 2016 to 2023). An autoimmune multi-organ disease typically associated with vasculopathy and autoantibody production. "We investigated whether MTMR3 SNP rs12537 in the miR-181a-binding site is associated with the susceptibility and progression of rheumatoid arthritis (RA) and systemic lupus erythematosus (SLE)." (PMID 31444373, 2019).
ulcerative colitis (3 papers, 2012 to 2019). An inflammatory bowel disease involving the mucosal surface of the large intestine and rectum. "Moreover, genetic variants at 22q12 were associated with early-onset IBD in a GWAS, and MTMR3 expression was demonstrated to be significantly reduced in colonic biopsies from ulcerative colitis patients." (PMID 31444373, 2019). "With regards to colonic expression, the only gene in this region which was shown to differ between the two major IBD types (CD and ulcerative colitis) and healthy controls was myotubularin-related protein 3 (MTMR3)." (PMID 24710487, 2012).
Obesity (2 papers, 2024 to 2025). Accumulation of substantial excess body fat. "Other variants mapped to MTMR3 have been associated with obesity-related traits in GWAS." (PMID 40216759, 2025). "Although there is no direct evidence linking MTMR3 to obesity, previous studies have established a connection between MTMR3 and related cardiometabolic traits." (PMID 40216759, 2025).
preeclampsia (2 papers, 2023 to 2024). Preeclampsia is a hypertensive disorder of pregnancy that is characterized by new-onset hypertension with proteinuria presenting after 20 weeks of gestation, and depending on mild or severe forms may initially present with severe headache, visual disturbances, and hyperreflexia. "The results presented in this featured article sought to identify ANRIL, miR-186, miR181a, and MTMR3 as new diagnostic biomarkers of preeclampsia with therapeutic potential." (PMID 37456780, 2023). "The diagnostic significance of the lncRNA ANRIL, miR-186, miR181a, and MTMR3 as predictors of discriminating between preeclampsia patients and controls were investigated using ROC curve analysis." (PMID 37456780, 2023). "Several studies demonstrated the role of lncRNAs and miRNAs in the pathogenesis of preeclampsia; the aim was to detect the expression profiles of serum LncRNA ANRIL, miR-186, miR-181a, and MTMR-3 in patients with preeclampsia." (PMID 37456780, 2023). "The initial objective of our study is to evaluate for the first time the expression profiles of lncRNA ANRIL, its target miRNAs (miR-186, miR-181a), and MTMR-3 (target gene for miR-181a) in preeclampsia patients." (PMID 37456780, 2023). "ROC curve of lncRNA ANRIL, miR-186, miR-181a, and MTMR-3 in preeclampsia patients showing the roles of these markers in the diagnosis of preeclampsia." (PMID 37456780, 2023). "Serum lncRNA ANRIL, miR-186, miR-181a, and MTMR-3 could be used as potential biomarkers for the diagnosis of preeclampsia that may be used as therapeutic targets." (PMID 37456780, 2023). "In conclusion, serum LncRNA ANRIL, miR-186, miR-181a, and MTMR-3 could be promising biomarkers in the diagnosis of preeclampsia." (PMID 37456780, 2023).
apical periodontitis (1 paper, 2025). "The most credible 3-UTR candidate variants were found in TBCK (rs79409042, chromosome 4) in the phenotype Necrosis of pulp or apical periodontitis, in HNRNPK (rs696825, chromosome 9) in Pulpal and apical diseases, and in MTMR3 (rs9983, chromosome 22) in Pulpitis." (PMID 40701953, 2025).
autoimmune disease (1 paper, 2019). A disorder resulting from loss of function or tissue destruction of an organ or multiple organs, arising from humoral or cellular immune responses of the individual to their own tissue constituents. "Our study also introduces MTMR3 as a novel biomarker of SLE progression; intensifying the notion that autophagy is linked to the pathogenesis of autoimmune diseases." (PMID 31444373, 2019). "Speculating that miR-181a could enhance autophagy level in T cells by inhibiting MTMR3 may give an additional explanation for the involvement of this miRNA in autoimmune diseases, but this notion should be further investigated." (PMID 31444373, 2019).
Autoimmunity (1 paper, 2019). The occurrence of an immune reaction against the organism's own cells or tissues. "A blood brain barrier phenotype is present as well as autoimmunity and autophagy with ANO2, HLA-DQB1, MTMR3, and SEC16A." (PMID 31026304, 2019).